KIFC1 (kinesin family member C1)
Diseases named in the same sentence as KIFC1 in open-access papers (continued):
Sharing a sentence is not in itself a finding about the gene and the disease.
cancer (continued). "Docking results demonstrated robust binding affinities and stable contacts with critical residues in the ATP-binding pocket, indicating a potential inhibition of KIFC1’s motor function vital for centrosome clustering and spindle organization in cancer cells." (PMID 41477589, 2025). "KIFC1 plays an essential role in centrosome clustering, a process that allows cancer cells to bypass multipolar divisions and maintain genomic stability." (PMID 40471955, 2025). "The ability of KIFC1 to rescue chromosomal instability in highly proliferative tumor cells further supports its relevance as a cancer therapeutic target." (PMID 40471955, 2025). "In humans, the kinesin motor protein KIFC1 (from the Kinesin-14 family), which plays a role in tumor cell division, has been observed to be significantly expressed in cancer cells of various cancers." (PMID 40244152, 2025). "Several small-molecule inhibitors that interact with KIFC1 and disrupt its function have been identified, effectively reversing the centrosome clustering phenotype in cancer cells." (PMID 40471955, 2025). "We employed this method to analyze the five commonly interacting top-ranked docked complexes to understand the function of small molecules derived from propolis in inhibiting the KIFC1 protein, thus controlling the KIFC1 pathway to regulate cancer expression." (PMID 40471955, 2025). "In cancer cells with supernumerary centrosomes, KIFC1 prevents multipolar mitotic spindle formation, which otherwise leads to mitotic catastrophe and cell death." (PMID 40471955, 2025). "Recent studies have reported prominent KIFC1 expression in various cancers, including breast, prostate, ovarian, and non-small cell lung cancers, making it a promising target for cancer therapy owing to its redundancy in normal somatic cells." (PMID 40471955, 2025). "Cancer cells often display centrosome amplification, requiring the kinesin KIFC1/HSET for centrosome clustering to prevent multipolar spindles and cell death." (PMID 39789388, 2025). "This study was designed to explore propolis-derived small molecules as KIFC1 inhibitors for cancer therapy using an in silico approach." (PMID 40471955, 2025). "Recent studies have suggested that KIFC1 is overexpressed in various cancers and that abnormally overexpressed KIFC1 plays a key role in promoting cancer progression." (PMID 40612867, 2025). "Clustering of amplified centrosomes in cancer cells avoids mitotic catastrophe and requires the kinesin KIFC1." (PMID 39789388, 2025). "The anomalous expression of KIFC1 correlates with tumour cell proliferation, metastasis, and adverse clinical outcomes across various cancer." (PMID 41477589, 2025). "Despite its established role in various cancers, the specific function of KIFC1 in CCa and its regulatory relationships remain inadequately understood." (PMID 40379626, 2025). "Cancer cell properties affected by KIFC1 include aerobic glycolysis, proliferation and invasion, drug resistance, and EMT." (PMID 40612867, 2025). "This study investigated the therapeutic significance of propolis-derived compounds targeting the kinesin-like protein KIFC1, a motor protein overexpressed in various cancers, using a multistep computational methodology." (PMID 40471955, 2025). "Kinesin family member C1 (KIFC1) is implicated in the development and progression of several types of cancer." (PMID 40857057, 2025). "OTUD6B catalytic activity is required to maintain KIFC1 levels and limit multipolar spindle formation, promoting the survival of cancer cells with supernumerary centrosomes." (PMID 39789388, 2025). "For tumor cells exhibiting abnormalities in centrosome division, KIFC1 is essential for survival, particularly for cancer cells possessing supernumerary centrosomes." (PMID 40379626, 2025). "Higher expression of KIFC1 was observed in several types of cancers and correlated with poor prognosis." (PMID 39349439, 2024).
cancer (continued). "First, we analyzed the expression of KIFC1 in various types of cancer using the TIMER and Human Protein Atlas databases." (PMID 38457554, 2024). "AZ82 is an inhibitor of KIFC1, a kinesin-14 family motor protein that has been shown to play a critical role in centrosome clustering in various types of cancer cells." (PMID 38385746, 2024). "Inhibiting KIFC1 has been demonstrated to preferentially sensitize cancer cells through centrosome declustering." (PMID 39074902, 2024). "The kinesin-14 family member KIFC1 is essential for centrosome clustering in cancer cells, and treatment of cells containing supernumerary centrosomes with a KIFC1 inhibitor results in cell death due to mitotic catastrophe." (PMID 38896608, 2024). "Cox regression analysis of KIFC1 levels across 33 types of cancers from the TCGA database demonstrated a correlation between KIFC1 and OS in patients across distinct cancer types." (PMID 39387242, 2024). "The up-regulation of KIFC1 in a variety of cancer cells with supernumerary centrosomes led researchers to develop small molecules specifically targeting KIFC1-dependent centrosomal clustering." (PMID 38896608, 2024). "During mitosis, KIFC1 clusters supernumerary centrosomes in cancer cells by crosslinking and sliding microtubules." (PMID 38902769, 2024). "We have previously shown that KIFC1 is a prognostic biomarker and an emerging therapeutic target in cancer, particularly TNBC." (PMID 38902769, 2024). "Although the expression of KIFC1 did not significantly differ between MP and BP cell lines, KIFC1 can serve as a target to promote KIF11/KIF15-dependent centrosome declustering in BP cancer cells." (PMID 39074902, 2024). "KIFC1 levels are frequently elevated in cancer cells, which is thought to promote centrosome clustering and bipolar spindle assembly by merging microtubules from separate centrosomes." (PMID 38896608, 2024). "Many cancer cells rely on HSET(KIFC1) to cluster the extra centrosomes into two groups to mimicthe bipolar spindle formation of non-centrosome-amplified cells andensure their survival." (PMID 36749938, 2023). "Prior investigations have revealed the prognostic significance and degree of expression of KIFC1 in a range of cancer types; however, the influence of abnormal expression of KIFC1 on immune cell infiltration is still ill-defined." (PMID 38112634, 2023). "KIFC1 is believed to be an oncogene in various types of cancers as it plays a crucial role in clustering multiple centrosomes to sustain tumor survival." (PMID 37330525, 2023). "Given the pivotal involvement and regulatory functions of KIFC1 in oncogenesis, it is imperative to conduct a comprehensive and extensive pan-cancer analysis to establish the potential role of KIFC1 across various tumor types." (PMID 38112634, 2023). "Kinesin family member C1 (KIFC1) is involved in multiple biological functions and plays a key role in cancer cell centrosome clustering." (PMID 37457582, 2023). "Kinesin family member C1 (KIFC1/HSET), a centrosome clustering protein that prevents cancer cells from undergoing centrosome-amplification-induced apoptosis, has been reported to be upregulated in TNBCs and African-American (AA) TNBCs." (PMID 38003261, 2023). "The kinesin family member C1 (KIFC1) is overexpressed in a range of human cancers and its upregulation is correlated with poor prognosis." (PMID 36984785, 2023). "The expression levels of KIFC1 in various cancers were assessed compared to normal tissues using the TCGA and GTEx databases." (PMID 38112634, 2023). "To investigate the role of KIFC1 in modulating the cancer immune microenvironment, we conducted correlation analyses between three kinds of immunomodulators as well as chemokines and expression of KIFC1 at the pan-cancer level." (PMID 38112634, 2023).
cancer (continued). "The results revealed a significant increase in KIFC1 scores in cancer tissues compared to adjacent tissues." (PMID 37955677, 2023). "The depletion of KIFC1 leads to a dramatic increase in the multipolar anaphases, and it selectively induces cancer cell death in the cells with centrosome amplification." (PMID 35327439, 2022). "A recent study demonstrates that the ATM and ATR kinases phosphorylate KIFC1 to maintain the viability of cancer cells with centrosome amplification, which leads to drug resistance and tumor recurrence." (PMID 35327439, 2022). "The depletion of KIFC1 leads to dramatic increases in multipolar anaphases, and to the selective cell death of the cancer cells with centrosome amplification, which provide a potential new target for effective cancer therapy." (PMID 35327439, 2022). "This ensued notably due to clustering of supernumerary centrosomes mediated by KIFC1, promoting bipolar divisions in cancer cells allowing their survival." (PMID 35511434, 2022). "In the CPTAC database, the total KIFC1 protein expressions were higher in primary cancers than in normal tissues for OV, COAD, UCEC, LIHC, HNSC, and LUAD." (PMID 35327439, 2022). "Kinesin family member C1 (KIFC1) is a microtubule binding protein that confers the survival of cancer cells with centrosome amplification, which is when a cell consists of more than 2 centrosomes per cell or has abnormally voluminous centrosomes." (PMID 36139643, 2022). "KIFC1 is a minus end-directed motor protein involved in spindle pole organization and formation and the clustering of excess centrosomes found in cancer cells." (PMID 33760984, 2021). "KIFC1 is upregulated upon induction of CA in cancer cells as a compensatory mechanism that assists cancer cells with extra centrosomes to avoid undergoing cell death." (PMID 34945833, 2021). "Kinesin family member C1 (KIFC1/HSET), which confers survival of cancer cells burdened with extra centrosomes, has been observed in premalignant and pre-invasive lesions, and its expression has been shown to correlate with increasing neoplastic progression." (PMID 34945833, 2021). "Kinesin family member C1 (KIFC1), a minus end-directed motor protein, is reported to play an essential role in cancer." (PMID 34768355, 2021). "Centrosome clustering in cancer cells is mediated by Kinesin family member C1 (KIFC1) (common paralogs: HSET, KIFC3, KIFC2, KIF14)." (PMID 33760984, 2021). "KIFC1 is an important kinesin for cancer cells that clusters excess centrosomes to allow for the successful division and survival of cancer cells." (PMID 33760984, 2021). "KIFC1 overexpression in cancer cells was found to accelerate cell cycle kinetics, particularly from G2 to M phase." (PMID 34945833, 2021). "KIFC1 phosphorylation induced upon DNA damaging agent treatment conferred cancer cell resistance to this therapy, and inhibition of this KIFC1 phosphorylation repressed centrosome clustering and tumor recurrence." (PMID 34945833, 2021). "Patients with above-median KIFC1 expression had lower recurrence-free survival when assessing all of the cancers at once (P = 6.4E-15)." (PMID 33760984, 2021). "As high expression of immune checkpoints was associated with T-cell exhaustion and worse prognosis, this also partly explained the cancer-promoting effect of KIFC1." (PMID 35111813, 2021). "Under DNA damaging treatments, the ATM and ATR kinases phosphorylate KIFC1 at Ser26 to selectively maintain the survival of cancer cells with amplified centrosomes via centrosome clustering, leading to drug resistance and tumor recurrence." (PMID 33397932, 2021). "KIFC1 is a novel kinesin that clusters excess centrosomes in cancer cells allowing the formation of bi-polar spindles, normal division, and cell survival." (PMID 33760984, 2021). "KIFC1 is strongly expressed in cancer cells and result in numerous cancer types including testis cancer in man." (PMID 32842864, 2020).
cancer (continued). "Here, we identified a crucial role of KIFC1 in controlling EE retrograde transport and dynamic distribution in both normal and cancer cells." (PMID 33215754, 2020). "Numerous findings indicate the essential role of HSET/kifC1 in the spindle structure of human cancer cells." (PMID 32575437, 2020). "Several reports show that KIFC1 is upregulated and is involved in cancer progression in some cancers." (PMID 30744126, 2019). "As well as clustering amplified centrosomes, KIFC1 is required to cluster acentrosomal spindle poles, which are also more common in cancer compared with normal cells." (PMID 31506331, 2019). "Antibodies were directed against the human kinesin HSET/KifC1, or the c-terminal residue of the human nuclear protein Ku-80, or the Human Leucocytes Antigen (HLA), frequently found on the membrane of human cancer cells." (PMID 31692907, 2019). "Although these three drugs have been shown to lead to multipolar mitosis and decrease cell viability in human cancer, their effects were somewhat different because each drug binds to a different allosteric site on KIFC1." (PMID 30744126, 2019). "In many kinds of cancer cells, KIFC1 has been demonstrated playing an essential role in bipolar spindle formation by clustering the multiple poles and maintaining chromosomal stability." (PMID 31895691, 2019). "KIFC1 also has independent functions in germ cells, which generally overexpressed in a variety of cancer cells, and is even positively correlated with the stage and malignancy of tumor." (PMID 31127080, 2019). "It is known that the expression of KIFC1 in cancer cells is much more than that in wild types, which is mainly reflected in that KIFC1 motors interfere in spindle assembly in mitosis, forming multiple centrosomes, thus accelerating cell division." (PMID 31127080, 2019). "Based on immuno-florescent staining results, we are able to propose a model of activity of KIFC1 during cancer cell cycle." (PMID 28977870, 2017). "C-terminus kinesin motor KIFC1 is known for centrosome clustering in cancer cells with supernumerary centrosomes." (PMID 28977870, 2017). "We found that the phenanthrenes, PJ34, Phen and Tiq-A, prevent the post-translational modifications of NuMA, HSET/kifC1 and Kif18A exclusively in human cancer cells." (PMID 28209915, 2017). "Other functions of KIFC1 in cancer cells including driving tumor malignancy by interacting with cyclins and inducing drug resistance against taxane and tamoxifane in breast and/or prostate cancer." (PMID 28977870, 2017). "In mitosis, KIFC1 plays an essential role in the clustering of supernumerary centrosomes in cancer cells." (PMID 28218233, 2017). "We found that PJ34, Phen and Tiq-A modify kinesins (HSET/kifC1 and kif18A) and NuMA (nuclear mitotic apparatus protein) in a variety of human cancer cells." (PMID 28209915, 2017). "Further investigations of how KIFC1 is regulated throughout the mitosis in cancer cells are needed for the understanding of the pathways where KIFC1 is involved and for further exploitation of indirect KIFC1 inhibitors." (PMID 27102297, 2016). "Despite the centrosome clustering function in cancer cells, KIFC1 is also observed to have a similar function in human primary lung fibroblast cell lines." (PMID 27102297, 2016). "KIFC1 was overexpressed in 42 out of 459 analyses (cancer tissue versus normal tissue) and TRIP13 in 69 out of 467 analyses (fold change threshold: 2; p value threshold: 1 × 10−4)." (PMID 26527623, 2016). "The kinesin motor KIFC1 has been suggested as a potential chemotherapy target due to its critical role in clustering of the multiple centrosomes found in cancer cells." (PMID 27102297, 2016). "In recent years, the key role played by the kinesin-14 protein HSET/KifC1 in centrosome clustering in cancer cells with supernumerary centrosomes, has been well established." (PMID 25788277, 2015).
cancer (continued). "Over the recent years, the role of KIFC1 in centrosome clustering in cancer cells with supernumerary centrosomes has been well recognized." (PMID 25028599, 2014). "Proof-of-concept comes from the recent discovery and preclinical development of two novel KIFC1 small molecule inhibitors AZ82 and CW069, that cause centrosome declustering exclusively in cancer cells with amplified centrosomes." (PMID 25028599, 2014). "It is likely that KIFC1 has clustering-independent role in cancer cells which require further investigation." (PMID 25028599, 2014). "We speculate that such a mechanism may enable cancer cells to maintain a check on KIFC1 ubiquitylation during anaphase and telophase, to ensure that supernumerary centrosomes remain clustered so that chromosomes are accurately divided into daughter cells." (PMID 39789388, 2025). "However, KIFC1 promotes the aggregation of dispersed centrosomes in cancer cells, facilitating polar division and ensuring cell survival." (PMID 40857057, 2025). "Collectively, these findings indicate that the selected compounds exhibit the requisite structural and energetic properties for KIFC1 inhibition and may represent viable candidates for experimental validation in cancer therapies." (PMID 41477589, 2025). "Moreover, a small animal imaging system was used to evaluate tumour growth, and the results also verified that KIFC1 knockdown obviously suppressed cancer cell proliferation." (PMID 40857057, 2025). "As kinesins are relatively difficult to target pharmaceutically, and complete inhibition of KIFC1 may have non-cancer cell specific effects, targeting OTUD6B has the potential to be developed as a more tolerable therapeutic route." (PMID 39789388, 2025). "In specific cancers, KIFC1 enhances tumor development through distinct pathways." (PMID 40379626, 2025). "Modulation of KIFC1 stability, and hence availability, may present an alternative strategy to reduce its activity in cancer cells." (PMID 39789388, 2025). "Targeting KIFC1 inhibition could disrupt cancer cell division, and propolis-derived small molecules are being explored as potential inhibitors." (PMID 40471955, 2025). "However, their pharmacological specificity for cancer over normal cells remains limited and next-generation KIFC1 inhibitors or novel ways to target centrosome-clustering are needed." (PMID 39789388, 2025). "The present computational analysis of selected propolis-derived compounds as potential KIFC1 inhibitors revealed that 4’,5,7-trihydroxy-3,6-dimethoxyflavone and 6-methoxy kaempferol may be promising candidates for cancer therapy." (PMID 40471955, 2025). "Notably, KIFC1 is overexpressed in various tumors, driving gene overexpression that controls mitotic checkpoints and induces aneuploidy, thus accelerating cancer progression." (PMID 40379626, 2025). "KIFC1 is an important kinesin for cancer cells and allows for division and survival." (PMID 40612867, 2025). "Moreover, upregulation of KIFC1 in AR-TNBC increased cancer cell proliferation and promoted epithelial-mesenchymal transition (EMT), contributing to the aggressive characteristics of AR-TNBC." (PMID 40448099, 2025). "Furthermore, micromolar concentrations of AZ82 and other KIFC1 inhibitors are required to achieve cytotoxic effects in cancer cells, raising the likelihood of undesirable off-target effects." (PMID 40002279, 2025). "Among this group KIFC1 (Kinesin Family Member C1) is notice as a pivotal protein in cancer biology." (PMID 41477589, 2025). "Although it is widely believed that KIFC1 is highly expressed in cancer cells, how KIFC1 gene expression is elevated remains largely unknown." (PMID 40612867, 2025). "Pan-cancer analysis of KIFC1 expression was performed in GEPIA2 database." (PMID 40612867, 2025). "Kinesin family member C1 (KIFC1) is crucial for cell division and highly expressed in cancer cells." (PMID 40471955, 2025). "A pan-cancer analysis of KIFC1 was performed using the GEIPA2 online database." (PMID 40612867, 2025).